Y_RNA (Y RNA )
Gene: Miscellaneous RNA gene on chromosome 6 (89,898,283 to 89,898,392, reverse strand). Ensembl gene ENSG00000252891.
Homologues: Orthologues: chimpanzee Y_RNA (100% identical). Paralogues in human: RNY1 (87% identical), Y_RNA (86% identical), Y_RNA (85% identical), RNY1P11 (84% identical), Y_RNA (84% identical), Y_RNA (83% identical), Y_RNA (82% identical), RNY1P8 (81% identical), Y_RNA (81% identical), Y_RNA (80% identical), RNY1P13 (79% identical), RNY1P7 (79% identical), and 97 more.